SLC2A14 (solute carrier family 2 member 14)
Description:
Hexose transporter that can mediate the transport of glucose and dehydroascorbate across the cell membrane.
Synonyms: GLUT14; SLC2A3P3
Tractability: Antibody: UniProt places it where antibodies can reach, with high confidence; its Gene Ontology location is reachable by antibodies, with high confidence; UniProt predicts a signal peptide or a membrane-spanning region; the Human Protein Atlas places it where antibodies can reach. PROTAC: ubiquitination databases record sites on it.
Target class: SLC superfamily of solute carriers; Electrochemical transporter; SLC02 family of hexose and sugar alcohol transporters; Transporter
Gene: Protein-coding gene on chromosome 12 (7,812,512 to 7,891,148, reverse strand). Ensembl gene ENSG00000173262.
Subcellular location: Cell membrane
Subcellular location (Human Protein Atlas): Plasma membrane
Pathways (Reactome):
Transport of small molecules: Cellular hexose transport
Gene Ontology:
Molecular function: D-glucose transmembrane transporter activity; dehydroascorbic acid transmembrane transporter activity; transmembrane transporter activity
Biological process: D-glucose transmembrane transport; dehydroascorbic acid transport; transmembrane transport
Cellular component: nucleus; plasma membrane; membrane
Genetic constraint (gnomAD): Loss-of-function variants: 10 observed, 39.91 expected, observed/expected ratio (o/e) 0.25, 90% interval 0.15 to 0.43. The upper end of that interval is the gene's LOEUF score, 0.43, which puts it in group 1 of 6, group 1 being the genes least tolerant of losing a copy. Missense variants: 421 observed, 617.09 expected, observed/expected ratio (o/e) 0.68, 90% interval 0.63 to 0.74. Synonymous variants: 186 observed, 231.55 expected, observed/expected ratio (o/e) 0.8, 90% interval 0.71 to 0.91.
Homologues: Orthologues: chimpanzee SLC2A14 (98% identical), macaque SLC2A14 (87% identical), zebrafish slc2a3b (59% identical), Caenorhabditis elegans fdgt-1 (34% identical), Drosophila melanogaster sut1 (34% identical), Drosophila melanogaster CG7882 (34% identical), zebrafish slc2a11l (32% identical), Drosophila melanogaster sut2 (32% identical), tropical clawed frog slc2a11.2 (31% identical), zebrafish slc2a9l1 (30% identical), Drosophila melanogaster sut3 (28% identical), Caenorhabditis elegans hmit-1.3 (26% identical), and 36 more. Paralogues in human: SLC2A3 (94% identical), SLC2A1 (62% identical), SLC2A4 (57% identical), SLC2A2 (50% identical), SLC2A7 (38% identical), SLC2A5 (37% identical), SLC2A9 (35% identical), SLC2A11 (32% identical), SLC2A13 (29% identical), SLC2A12 (27% identical), SLC2A8 (26% identical), SLC2A10 (24% identical), and 1 more.
Diseases named in the same sentence as SLC2A14 in open-access papers:
SLC2A14 is named in the same sentence as 14 diseases in open-access papers, as found by Europe PMC text mining. Sharing a sentence is not in itself a finding about the gene and the disease. The quoted sentences say what the papers report.
inflammatory bowel disease (2 papers, 2021 to 2022). A spectrum of small and large bowel inflammatory diseases of unknown etiology. "In human genetic studies, SNPs in the SLC2A14 gene region were reported to be associated with some diseases, including Alzheimer’s disease and inflammatory bowel disease." (PMID 36230616, 2022).
lymphoma (2 papers, 2017 to 2022). A malignant (clonal) proliferation of B- lymphocytes or T- lymphocytes which involves the lymph nodes, bone marrow and/or extranodal sites. "Disorders of the central nervous system, rheumatoid arthritis, lymphoma, and intraocular pressure in primary open-angle glaucoma have all been linked to mutations in the SLC2A14 gene." (PMID 36699685, 2022). "Altered expressions of SLC2A family members have been reported in many types of cancer (liver- SLC2A1, SLC2A2, SLC2A5; pancreas- SLC2A1; breast- SLC2A1, SLC2A2, SLC2A4; stomach- SLC2A2, SLC2A4, SLC2A5, SLC2A14; lymphoma- SLC2A5)." (PMID 28978124, 2017).
alcohol dependence (1 paper, 2022). Physical and psychological dependence on alcohol. "Notably, several SNPs in the SLC2A14 gene region were also reported to be associated with alcohol dependence at the p ≤ 10−4 level of significance, which is known to be at least partly pertinent to the opioid system in its etiology." (PMID 36230616, 2022). "Although the impact of this SNP on SLC2A14 function and the opioid system remains unknown, this SNP may have some influence on both the risk for alcohol dependence and opioid sensitivity." (PMID 36230616, 2022).
colon cancer (1 paper, 2019). "In addition, this group comprises the classical glucose transporters SLC2A3 (GLUT3) which were found to mediate elevated glycolysis in colon cancer cells and SLC2A14 (Glut14) which is a duplication of GLUT3 and is known to be specifically expressed in testis." (PMID 31560702, 2019).
periodontitis (1 paper, 2024). An acute or chronic inflammatory process that affects the tissues that surround and support the teeth. "The ANN diagnostic model comprising four key genes—SLC1A5, SLC2A14, LURAP1L, and HERPUD1—demonstrated a high predictive efficacy for periodontitis with an AUC of 0.928 in the dataset." (PMID 38802844, 2024). "The ferroptosis-related genes identified in this study, including SLC1A5, SLC2A14, LURAP1L, and HERPUD1, may serve as novel diagnostic and therapeutic targets for periodontitis." (PMID 38802844, 2024). "Subsequently, through protein–protein interaction networks and multi-dataset machine learning algorithms, we further narrowed down these candidates to four key ferroptosis-related genes differentially expressed in periodontitis, namely SLC1A5, SLC2A14, LURAP1L, and HERPUD1." (PMID 38802844, 2024). "The ferroptosis-related genes SLC1A5, SLC2A14, LURAP1L, and HERPUD1 may serve as novel biomarkers for the diagnosis of periodontitis." (PMID 38802844, 2024). "Based on this, our study hypothesizes that ferroptosis-related genes, including SLC1A5, SLC2A14, LURAP1L, and HERPUD1, could be novel biomarkers for periodontitis." (PMID 38802844, 2024).
thyroid carcinoma (1 paper, 2020). "SLC2A14 (or GLUT14) expression is deregulated in several cancer types and is suggested to be a prognostic factor for a number of cancers, for example, in thyroid carcinoma." (PMID 32580154, 2020).
tumor (7 papers, 2009 to 2024). "A lower differentiation grade tumor is implied by overexpression of SLC2A1, SLC2A5, SLC2A10, SLC2A11and lower levels of SLC2A3, SLC2A6, SLC2A9, SLC2A12, and SLC2A14, emphasizing the possibility of these molecular roles for predicting the course of the tumor." (PMID 36518662, 2022). "The genes of the SLC family such as SLC2A14 and SLC2A3 and the AKR1 (aldo-keto reductase 1) family such as AKR1C1, AKR1C2, AKR1C3 and AKR1B10 were associated with the metabolic processes of tumor cells." (PMID 20003295, 2009). "Additionally, lower levels of SLC2A3, SLC2A6, SLC2A9, SLC2A12, and SLC2A14 and higher levels of SLC2A1, SLC2A5, SLC2A10, and SLC2A11 had an association with advanced tumor stage." (PMID 36518662, 2022). "Furthermore, SLC2A3, SLC2A6, SLC2A9, SLC2A12, and SLC2A14 levels were lower in patients with advanced tumor stages, suggesting that these genes might act as a barrier to the progression of LUAD." (PMID 36518662, 2022). "According to data from the UALCAN database, LUAD patients’ tumor tissues had hypomethylation of SLC2A1, SLC2A2, SLC2A5, SLC2A6, SLC2A7, SLC2A11 and hypermethylation of SLC2A3, SLC2A10, and SLC2A14 compared to normal tissues." (PMID 36518662, 2022). "LUAD tumor tissues showed higher mRNA expressions of SLC2A1, SLC2A5, and SLC2A12 and lower expressions of SLC2A3, SLC2A4, SLC2A6, SLC2A9, and SLC2A14." (PMID 36518662, 2022). "In our study, we show that transcriptional levels of SLC2A1, SLC2A5 are upregulated and those of SLC2A3, SLC2A6, SLC2A9, SLC2A14 are downregulated in LUAD patients, supporting the role of SLC2A1, SLC2A5 as oncogenes and SLC2A3, SLC2A6, SLC2A9, SLC2A14 as tumor suppressor genes." (PMID 36518662, 2022).
cancer (6 papers, 2017 to 2024). A tumor composed of atypical neoplastic, often pleomorphic cells that invade other tissues. "Additionally, numerous SNPs in or near the SLC2A14 gene region collectively increased the amount of analgesic that was required for cancer pain management." (PMID 36230616, 2022). "Although the present results need to be corroborated by more research with larger sample sizes, these findings indicate that these SNPs in the ANGPT1 and SLC2A14 genes could serve as markers that predict the efficacy of opioid analgesics in the treatment of cancer pain." (PMID 36230616, 2022). "In conclusion, our GWASs discovered SNPs and a gene that were associated with opioid analgesic requirements in the treatment of cancer pain, including the ANGPT1 rs1283671 and rs1283720 SNPs and SLC2A14 gene." (PMID 36230616, 2022). "The roles of SLC2A14 and SLC2A3 in cancer have more recently gained attention." (PMID 32580154, 2020).
SLC2A14 also shares sentences with these, for which no sentence is quoted: Alzheimer disease (1 paper); Disorders of the central nervous system (1); glioblastoma (1); glioma (1); primary open-angle glaucoma (1); rheumatoid arthritis (1).